LGI1 (leucine rich glioma inactivated 1)
Diseases named in the same sentence as LGI1 in open-access papers (continued):
Sharing a sentence is not in itself a finding about the gene and the disease.
encephalitis (continued). "We retrospectively assessed all anti-LGI1 encephalitis patients from this center with anti-LGI1-IgG-subclass information and follow-up MRI available." (PMID 39105896, 2024). "Especially in patients suffering from anti-LGI1 encephalitis refractory to ASM, striking effects of immunotherapy on seizure freedom were noted mostly within 1 week of initiation." (PMID 37278857, 2024). "This case adds to the existing literature on cases of anti-LGI-1 encephalitis, a rare form of autoimmune encephalitis, and its varied clinical manifestations." (PMID 39867015, 2024). "This is a retrospective chart review of patients with LGI1-Ab encephalitis diagnosed at our center between 2005 and 2022." (PMID 38603771, 2024). "We focused on analyzing the clinical characteristics of patients with acute symptomatic seizures secondary to AE and compared the clinical characteristics of the most common subtypes, anti-NMDAR and anti-LGI1 encephalitis." (PMID 39539648, 2024). "In our study, the median serum sodium and chloride levels were significantly lower in patients with anti-LGI1 encephalitis compared to those with anti-NMDAR encephalitis (p < 0.001, p = 0.019)." (PMID 39539648, 2024). "In our study, 80.77% (21/26) of patients with anti-LGI1 encephalitis experienced seizures, consistent with previous research findings." (PMID 39539648, 2024). "Given his previous history of anti-LGI1 encephalitis, and having ruled out other sinister causes of his sweating, the patient was treated for a possible relapse of his anti-LGI1 encephalitis." (PMID 39867015, 2024). "Two-thirds of published patients with anti-leucine rich, glioma inactivated 1 (LGI1) encephalitis develop hippocampal sclerosis (HS)." (PMID 39105896, 2024). "It was observed that the presence of FBDS was associated with progressive cognitive deficits, but patients with anti-LGI1 encephalitis and normal cognition barely harbor anti-LG1 IgG1 antibodies." (PMID 37278857, 2024). "In a population of patients with anti-LGI1 encephalitis it has been shown that nearly all patients develop mesiotemporal atrophy and up to 50% mesiotemporal sclerosis." (PMID 37278857, 2024). "In anti-LGI1 encephalitis relapse rate was reported in up to 35% over 2 years and in 25% of patients suffering from contactin-associated protein-like 2 (CASPR2)-mediated encephalitis." (PMID 37278857, 2024). "LGI1-antibody encephalitis patients exhibit focal and tonic-clonic seizures as well as cognitive impairment." (PMID 38662480, 2024). "Among the AE subtypes with seizures, anti-NMDAR encephalitis was more common in the young, with an equal number of males and females affected, while anti-LGI1 encephalitis was more common in elderly males." (PMID 39539648, 2024). "Seizures are common in the early stages of AE, with faciobrachial dystonic seizures (FBDS) characteristic of anti-LGI1 encephalitis and SE and super-refractory status epilepticus (Sup-RSE) frequently observed in anti-NMDAR encephalitis." (PMID 39539648, 2024). "We conducted a comparative analysis of the data of anti-NMDAR encephalitis and anti-LGI1 encephalitis with seizures." (PMID 39539648, 2024). "In the seizure group, anti-LGI1 encephalitis was more likely to show abnormal MRI signals compared to anti-NMDAR encephalitis (p = 0.008)." (PMID 39539648, 2024). "Using immunohistochemistry and live neuron staining, CNS reactivities were detected in only 0 to 12.5% of all B-lineage cells in the two LGI1 antibody encephalitis patients." (PMID 38319973, 2024). "The median age at onset of LGI1-Ab encephalitis was 66 years (range: 29–86, IQR: 17), and 23/30 (77%) patients were male." (PMID 38603771, 2024). "Our patient had an atypical presentation of acute hyperhidrosis, uncovering an underlying autonomic dysfunction, leading to the diagnosis of a relapse of his anti-LGI1 encephalitis." (PMID 39867015, 2024).
encephalitis (continued). "FBDS are characteristic of anti-LGI1 encephalitis, observed in 14.29% (3/21) of our cases, lower than the 28–69% reported in other studies." (PMID 39539648, 2024). "Anti-LGI1 encephalitis also presents with classic MRI findings of limbic encephalitis including T2/FLAIR hyperintense signal change of the hippocampus and amygdala followed by hippocampal atrophy on long-term follow-up." (PMID 38327544, 2024). "Anti-LGI1 encephalitis and anti-CASPR2 encephalitis were more sensitive to first-line and second-line treatments." (PMID 38152405, 2023). "Compared with the findings of previous studies, the present work revealed concrete sub-regional and lateralized changes in metabolic characteristics in patients with anti-LGI1 encephalitis based on 18F-FDG PET images." (PMID 37064193, 2023). "During the follow-up period, 5 (9.1%) patients experienced a relapse, 3 with anti-NMDAR encephalitis, 1 with anti-LGI1 encephalitis and 1 with anti-GABABR encephalitis." (PMID 37503335, 2023). "Thirteen patients with clinically confirmed anti-LGI1 encephalitis were included (seven men and six women; median age, 57 years)." (PMID 37064193, 2023). "Accordingly, hypermetabolism in specific regions in anti-LGI1 encephalitis is likely to indicate the presence of antibody-induced neuronal disturbance and the subsequent impairment of neurological function." (PMID 37064193, 2023). "Based on these findings, he was diagnosed with anti-LGI1 encephalitis and was treated with methylprednisolone of 500mg for 5 days, with a half-dose reduction every 3 days, followed by oral prednisone." (PMID 37304289, 2023). "The serum of patients with LGI1 encephalitis had reduced levels of CD28, ICOS-L, PDCD1 (all p < 0.05), and CD86 (p < 0.01), but higher levels of ICOS (p < 0.05) and PD-L2 (p < 0.001) were detected." (PMID 37644514, 2023). "This retrospective study enrolled thirteen patients confirmed with LGI1 antibody encephalitis who were admitted to Beijing Tiantan Hospital from June 2021 to September 2022." (PMID 37064193, 2023). "One of the most common, after anti-NMDAR, is anti-leucine-rich glioma-inactivated 1 (LGI1) encephalitis, which along with CASPR2 is part of the voltage-gated potassium channel complex (VGKCC)." (PMID 37239077, 2023). "With a presumed diagnosis of anti-LGI1 encephalitis, the patient was treated with oral oxcarbazepine of 0.6 grams per day and intravenous immunoglobulin (IVIG) for 5 days." (PMID 37179544, 2023). "Three anti-LGI1 encephalitis patients were hospitalized in the Department of Pediatrics at Qilu Hospital of Shandong University." (PMID 37179544, 2023). "The heating cluster map indicated 71 exo-miRNAs with differential expression between the LGI1 encephalitis cases and the control individuals." (PMID 37644514, 2023). "Our findings revealed that the promoter of hsa-miR-2467-5p was present with hypo-methylation changes in LGI1 encephalitis for the first time." (PMID 37644514, 2023). "Although the exact number of reported cases of LGI1 encephalitis is unclear, a recent systemic review has identified approximately 500 cases reported in literature." (PMID 40217477, 2023). "In LGI1 encephalitis, antibodies bind to the LGI1 proteins on the surface of neurons, leading to inflammation and damage to brain tissue." (PMID 37064193, 2023). "FBDS are characteristic symptoms of anti-LGI1 encephalitis and are considered pathognomonic, with brief inflexible posturing events typically lasting several seconds, usually less than 3 seconds, and occurring dozens of times during the day." (PMID 37304289, 2023). "None of the age, gender, weight, and height of patients with LGI1 antibody encephalitis was significantly different from that of patients with GABAB receptor antibody encephalitis with the p values of 0.08, 0.88, 0.91, and 0.80, respectively." (PMID 37592180, 2023).
encephalitis (continued). "As with the improvement of recognition and easy access to test technology, more and more cases of anti-LGI1 encephalitis are reported in the recent decade." (PMID 37179544, 2023). "Further studies documented motor cortex as another major target besides temporal cortex and limbic system in anti-LGI1 encephalitis." (PMID 37179544, 2023). "The patient was diagnosed with anti-LGI1 encephalitis and was treated with methylprednisolone at 500mg for 5 days, with a gradual tapering every 3 days, followed by oral prednisone." (PMID 37304289, 2023). "In this study, compared with healthy participants, the metabolism of both the MTL and BG was abnormal in patients with LGI1 antibody encephalitis and those with GABAB receptor antibody encephalitis." (PMID 37592180, 2023). "Simultaneously, an increase in miR-2467-5p was observed in PBMCs and exosomes obtained from LGI1 encephalitis cases." (PMID 37644514, 2023). "This study has confirmed that IgG4 is the major subclass of LGI1-IgG, and a higher LGI1-IgG specific CSF index, that is, the index of intrathecal antibody synthesis, is related to the poor prognosis of patients with anti-LGI1 encephalitis." (PMID 37090723, 2023). "Anti-NMDAR and anti-GABABR encephalitis had a higher proportion of CSF abnormalities compared with anti-LGI1 and anti-CASPR2 encephalitis, which is consistent with the results of previous studies." (PMID 38152405, 2023). "Next, we examined the data on abundant exosome-derived microRNAs (exo-miRNAs) between LGI1 encephalitis cases and HDs." (PMID 37644514, 2023). "A plethora of involuntary movements have been described in LGI1-encephalitis, including faciobrachial dystonic seizures (FBDS), chorea, myoclonus, parkinsonism, and paroxysmal dyskinesia." (PMID 37033571, 2023). "Herein, we describe five cases of anti-LGI1 encephalitis with paroxysmal limb weakness as an initial symptom." (PMID 37304289, 2023). "We present the case of a 6-year-old Chinese girl who was diagnosed with anti-LGI1 encephalitis which was characterized by seizures and hyponatremia." (PMID 37391712, 2023). "Almost all reported cases of pediatric anti-LGI1 encephalitis showed relatively good outcomes and went back to school smoothly, although part of them were receiving long-term immunosuppressants or steroids." (PMID 37179544, 2023). "Here we give detailed description of the clinical features and long-term outcome of three cases of childhood onset anti-LGI1 encephalitis." (PMID 37179544, 2023). "For example, facio-brachial dystonic seizures, which are brief motor seizures lasting for 1–3 s and typically involve simultaneous movements of the limbs and face, are highly characteristic of anti-LGI1 encephalitis." (PMID 37626673, 2023). "Significant methylation alterations were found in the promoters of CSF3, CCL2, and ICAM1 in LGI1 encephalitis patients comparable to healthy individuals." (PMID 37644514, 2023). "Our findings are in line with a previous paper that described substantial asymmetry in anti-LGI1 encephalitis." (PMID 37033571, 2023). "Anti-leucine-rich glioma-inactivated 1 (LGI1) encephalitis is a limbic encephalitis that rarely presents as an isolated psychiatric syndrome." (PMID 37275973, 2023). "FBDS is regarded as a typical presentation at the early stage of anti-LGI1 encephalitis, presented as dystonia on the same side of the face, upper or lower limb, and accompanied by increased metabolism of 18F-FDG in the basal ganglia." (PMID 37064193, 2023). "By analyzing all literature-reported 19 pediatric cases, we found pediatric anti-LGI1 encephalitis is more common in female and adolescent." (PMID 37179544, 2023). "Anti-LGI1 encephalitis is considered the second most common form of autoimmune encephalitis observed in adults with an average onset age of around 63 years and a higher incidence in males." (PMID 37391712, 2023).
encephalitis (continued). "In this report, we describe a novel case of a patient withanti-LGI1 encephalitis with a predominant long-term psychiatric presentation." (PMID 37275973, 2023). "For instance, anti-NMDAR antibody encephalitis presents with CSF pleocytosis in about 80% of the cases, while anti-LGI-1 and anti-CASPR2 antibody positive encephalitis often exhibit normal CSF standard parameters." (PMID 37821561, 2023). "Anti-leucine-rich glioma-inactivated 1 (LGI1) encephalitis is the second most common kind of autoimmune encephalitis following anti-N-methyl-d-aspartate receptor (NMDAR) encephalitis." (PMID 37304289, 2023). "Anti-leucine-rich glioma-inactivated 1 (LGI1) encephalitis is infrequently reported but more and more recognizable in children." (PMID 37179544, 2023). "A predominantl neurocognitive and manic presentation of anti-LGI1 encephalitis can lead to delayed diagnosis and treatment, therefore inducing a poorer response to medication." (PMID 37275973, 2023). "As anticipated, we found extensive abnormalities of DNA methylation in LGI1 encephalitis, including global DNA hypomethylation and CGI-specific hypermethylation, indicating their crucial roles in the etiology of LGI1 encephalitis." (PMID 37644514, 2023). "Leucine-rich glioma-inactivated 1 (LGI1) antibody encephalitis is a type of autoimmune encephalitis that affects the central nervous system." (PMID 37064193, 2023). "The presence of concurrent hypermetabolism in the hippocampus and striatum with neocortical hypometabolism was shown to be a conventional metabolic abnormality in those with anti-LGI1 encephalitis in our previous findings." (PMID 37064193, 2023). "In conclusion, the ResNet18 model was a potential approach for discriminating between LGI1 antibody encephalitis and GABAB receptor antibody encephalitis." (PMID 37592180, 2023). "The proportion of consciousness disorders was much lower in anti-LGI1 encephalitis (25.0%) than in other subtypes, which all had proportions > 40%." (PMID 38152405, 2023). "Compared with reports of literature, 59% of pediatric patients showed normal brain MRI and for those with abnormal results, the majority showed lesions of temporal lobe and hippocampus, which were also in accordance with adult anti-LGI1 encephalitis." (PMID 37179544, 2023). "Further prospective studies are required to fully characterize the differences in metabolic patterns in anti-LGI1 encephalitis." (PMID 37064193, 2023). "Faciobrachial dystonic seizures (FBDS), presenting as stereotyped clonic-like movements of face and ipsilateral limb while lacking electrical correlate, are unique and specific in anti-LGI1 encephalitis but infrequently reported in children." (PMID 37179544, 2023). "Three cases of patients presenting anti-LGI1 encephalitis with psychiatric presentation have been published, two with psychotic symptoms and memory loss (one of whom presenting faciobrachial seizures), and one with manic syndrome." (PMID 37275973, 2023). "Overall, the present study suggests an asymmetric 18F-FDG metabolic pattern in patients with anti-LGI1 encephalitis." (PMID 37064193, 2023). "Post-mortem analysis in these cases showed complement deposition, a feature also shared by post-mortem examination of the small number of available brains from patients with LGI1-related encephalitis." (PMID 36979644, 2023). "Childhood onset anti-LGI1 encephalitis is a heterogeneous clinical syndrome, ranging from typical limbic encephalitis to isolating focal seizures." (PMID 37179544, 2023). "Following a careful review of the literature, we identified 15 articles describing 24 pediatric patients (<18 years) with anti-LGI1 encephalitis." (PMID 37391712, 2023). "Diagnosis of LGI1 encephalitis was confirmed with a positive Anti-LGI1 antibody in the cerebrospinal fluid, and treatment with intravenous immunoglobulin and steroids improved her cognitive function." (PMID 36852369, 2023).
encephalitis (continued). "The other four patients refused lumbar punctures, including 2 patients with anti-GABABR encephalitis, 1 patient with anti-LGI1 encephalitis, and 1 patient with anti-CASPR2 encephalitis." (PMID 38152405, 2023). "After the presumed diagnosis of anti-LGI1 encephalitis, the patient was treated with intravenous immunoglobulin (2 g/kg over 5 days) and intravenous methylprednisolone (8 mg/kg/d)." (PMID 37179544, 2023). "At the patient level, 94.12% (16/17) of patients with GABAB receptor antibody encephalitis and 96.88% (62/64) of patients with LGI1 antibody encephalitis were accurately detected." (PMID 37592180, 2023). "As for adults, patients with anti-LGI1 encephalitis do show better long-term outcomes and lower recurrent rates than those with anti-NMDAR encephalitis." (PMID 37179544, 2023). "Binding interference has been described as an effect of exposure to polyclonal patient’s LGI1 autoantibodies, but it is possible that interference and internalization occur simultaneously in anti-LGI1 encephalitis patients." (PMID 38201219, 2023). "Anti-LGI1 encephalitis is rare in children which makes it difficult to perform a stratified analysis." (PMID 37179544, 2023). "Anti-LGI1 encephalitis and anti-CASPR2 encephalitis were more sensitive to first-line and second-line treatment." (PMID 38152405, 2023). "In this report, we describe a novel case of a patient with chronified anti-LGI1 encephalitis which improved both clinically and radiologically after 1 year of second-line treatment." (PMID 37275973, 2023). "Anti-leucine-rich glioma-inactivated 1 (LGI1) encephalitis, anti-N-methyl-D-aspartate (NMDA) receptor encephalitis, and anti-contactin-associated protein-like 2 (CASPR2) encephalitis are only a few of the more prevalent varieties." (PMID 37175665, 2023). "As the most common limbic encephalitis, anti-LGI1 encephalitis is an acute or subacute disorder, and mainly affects adults between the ages of 30 to 80 with a higher incidence in men." (PMID 37304289, 2023). "At the beginning of the disease, some prodromal symptoms can be found in patients with anti-LGI1 encephalitis, such as paroxysmal dizziness spells, seizures, fatigue, or drowsiness." (PMID 37304289, 2023). "Specifically, at the slice level, 73.28% (1445/1972) of image slices with GABAB receptor antibody encephalitis and 87.72% (1628/1856) of image slices with LGI1 antibody encephalitis were accurately detected." (PMID 37592180, 2023). "Hyponatremia and faciobrachial dystonic seizures were seen among the anti-LGI1 encephalitis patients." (PMID 37153594, 2023). "We found that increased DNA methylation level in the promoter of miR-2467-5p was not significantly correlated with its reduced expression in exosomes for LGI1 encephalitis cases and control participants (r = 0.393, p = 0.232)." (PMID 37644514, 2023). "The patients with LGI1 encephalitis with CSF-restricted OCBs exhibited higher level of CCL15 alone compared to those patients without CSF OCBs (p < 0.05)." (PMID 37644514, 2023). "Previous studies have shown that FBDS and hyponatraemia are the characteristic symptoms of anti-LGI1 encephalitis." (PMID 38152405, 2023). "Previous studies found that the metabolism of the medial temporal lobe (MTL) and basal ganglia (BG) was abnormal in patients with LGI1 antibody encephalitis and those with GABAB receptor antibody encephalitis." (PMID 37592180, 2023). "Patients with anti-LGI1 encephalitis are typically middle-aged and present with limbic encephalitis comprising prominent amnesia and epileptic seizures." (PMID 38201219, 2023). "Recently, we found an atypical manifestation of anti-LGI1 encephalitis, in which paroxysmal limb weakness was the initial symptom." (PMID 37304289, 2023). "MRI findings were suggestive of LGI1 antibody encephalitis in patients who underwent 18F-FDG PET/MRI." (PMID 37064193, 2023). "Anti-leucine-rich glioma inactivated 1 (LGI1) encephalitis is a frequent and severe autoimmune encephalitis." (PMID 36849262, 2023).